INSR (insulin receptor)
Diseases named in the same sentence as INSR in open-access papers (continued):
Sharing a sentence is not in itself a finding about the gene and the disease.
diabetes (continued). "Mice lacking IGF1R and INSR in adipocytes contain almost no adipose tissue and develop significant diabetes, dyslipidemia, and fatty liver." (PMID 35370981, 2022). "The notable canonical pathways shared between both CUR groups in the different dietary regimens included insulin secretion and insulin receptor signaling pathways, the senescence pathway, IGF-1, mTOR, and Hif1 α signaling, and Type 2 diabetes mellitus signaling." (PMID 35017319, 2022). "Remission of diabetes was achieved without severe hypoglycemic events and his circulating insulin receptor antibodies became negative after seven months of initiation of these treatments." (PMID 36157458, 2022). "It is not uncommon for people with insulin receptor (INSR) defects to maintain plasma insulin concentrations 1–2 orders of magnitude above normal for years before diabetes develops." (PMID 35618782, 2022). "More importantly, key genes of the respective pathways, such as AKT3, FGF2, FGF7, mitogen-activated protein kinase 4 (MAP3K4), MAP3K5, insulin receptor (INSR), AKT3, and mTOR, were also enriched in the analysis, thus explaining the link between diabetes and BCRL subjects in the present study." (PMID 36232660, 2022). "In the insulin receptor signaling pathway, PIk3R2 is an important regulatory subunit of PI3K/p85, and it can significantly suppress the activation of the PI3K/Akt pathway participating in the physiological and pathological diabetes processes." (PMID 34084770, 2021). "The pathophysiology of type 2 diabetes mellitus (T2D) is characterized by reduced or absent insulin receptor (INSR) responsiveness to its ligand, elevated hepatic glucose output and impaired glucose uptake in peripheral tissues, particularly skeletal muscle." (PMID 31378829, 2020). "In order to determine whether venom insulins are capable of lowering blood glucose in fish via activation of the insulin receptor, cone snail insulins were tested in the streptozotocin (STZ)-induced model of diabetes in zebrafish." (PMID 30747102, 2019). "In this study, we found that chronic heavy alcohol consumption was associated with the risk of developing diabetes in carriers of the GCK rs758989 C allele and in non-carriers of the INSR AACT haplotype." (PMID 31882596, 2019). "The HR for the incidence of diabetes was 1.98 (95% CI 1.24–3.18) for chronic heavy drinkers not carrying the AACT haplotype (−/−) of INSR compared with never-drinkers carrying the haplotypes (ht/ht) and (ht/−)." (PMID 31882596, 2019). "Western blot (WB) analysis showed further impairments in IR and phosphor‐insulin receptor (pIR) levels in diabetic AD samples compared to AD samples without diabetes (Figure 1a1, a2)." (PMID 30809950, 2019). "INSR knockout mice die soon after birth because of ketoacidosis, whereas diabetic ketoacidosis does not seem to occur in human patients with Donohue syndrome, at least not in the first years of life." (PMID 29695048, 2018). "In total, 29 targets were identified including INSR, RASH, KPYR, ANGI and so on, which might be related to anti-diabetes, anti-cancer, anti-anemia, neuroprotection, anti-leukemia, anti-coagulopathy, and osteogenic activities." (PMID 30347747, 2018). "For example Insulin receptor (INSR) had gain in RCC+diabetes and in diabetes groups." (PMID 25821562, 2015). "Interestingly, insulin receptor (INSR) is highly expressed and had gains in copy number in RCC+diabetes and diabetes groups." (PMID 25821562, 2015). "One study reported that TCR from humans with diabetes and non-obese mice with diabetes mimic insulin and the insulin receptor." (PMID 21901158, 2011). "(vi) Finally, there is circumstantial evidence that Enpp3 may be also related to diabetes, though a direct link to the insulin receptor, as that known to occur in the case of ENPP1, has not been reported." (PMID 39641818, 2024).
diabetes (continued). "INSR and insulin also had a negative correlation in the normal glucose tolerance group in the FUSION human cohort, suggesting that this consistent association is independent of pathological changes or diabetes." (PMID 34921686, 2022). "Further, our analysis with the 21 and seven genes (that link the diabetes pathway with COVID-19) suggests that TNF and INSR are key targets in COVID-19 patients with pre-existing diabetes, and the anti-TNF anti-INSR drugs may be repurposed in managing the COVID-19 severity in diabetic patients." (PMID 34067609, 2021). "Kinase activity (GO:0016301) and insulin receptor substrate binding (GO:0043560) were found to be related to at least one of the KEGG pathways such as insulin resistance, insulin signaling pathway, FoxO signaling pathway, PI3K-Akt signaling pathway, and type 2 diabetes mellitus." (PMID 33150068, 2020). "Chronic heavy drinkers who were non-carriers of the INSR AACT haplotype had a higher incidence of diabetes, indicated by decreased disposition index reflecting β-cell function and composite insulin sensitivity, compared with carriers of the AACT haplotype or never-drinkers." (PMID 31882596, 2019). "Furthermore, the absence of the insulin receptor in mouse β-cells caused a reduction in GSIS and promoted glucose intolerance, eventually leading to diabetes." (PMID 31426858, 2019). "Cases of diabetes due to an impaired insulin receptor or an absent insulin receptor are rare." (PMID 26871809, 2016). "Furthermore, although obesity and diabetes have an impact on the INSRB:A ratio, the exact stimuli that regulate the alternative splicing of the INSR are still unknown." (PMID 25742416, 2015). "Interestingly, insulin receptor (INSR) a gene found in both responses to cytokine stimulus (GO:0034097) and ubiquitin-dependent protein catabolic process (GO:0006511) had gains in both RCC+diabetes and diabetes groups." (PMID 25821562, 2015). "The insulin receptor (INSR) is a central node for glycemic control in cells of the major metabolic insulin responsive tissues and therefore, is a key target for antibodies that could either mimic or potentiate insulin action in diabetes." (PMID 24533136, 2014). "Also, the lack of insulin in patients with diabetes may contribute to enhanced platelet activation as insulin binds to the insulin receptor (IR) located on the platelet surface and activates insulin receptor substrate 1 (IRS-1) via tyrosine phosphorylation." (PMID 38398275, 2024). "Diabetes mellitus (DM) is diagnosed based on a high serum glucose level due to a lack of insulin secretion, absence of insulin receptor responsiveness, or both." (PMID 35434481, 2022). "The phenotype of diabetes by blocking IGF-1 signaling is more obvious in mouse models lacking both IGF1R and INSR in β-cells." (PMID 35370981, 2022). "This phenotype has been ascribed to restore insulinsensitivity through insulin receptor (IR) and insulin receptorsubstrate (IRS1) in the absence of PTP1B, thus projecting theimportance of PTP1B as drug target for diabetes and obesity." (PMID 29379255, 2017). "The findings that only 40–50% of patients with diabetes see a remission in diabetes after RYGB, and of those 10% see a reoccurrence each year despite an improvement in insulin secretion and insulin receptor concentration, suggest that this does not occur." (PMID 25876175, 2015). "Therefore, NPC43, through its interaction with INSRα and selective activation of INSR but not IGF1R, may represent a novel oral, safe and effective agent for the treatment of diabetes in humans." (PMID 31378829, 2020).
Obesity (290 papers, 2006 to 2026). Accumulation of substantial excess body fat. "Collectively, these findings suggest early life overnutrition can induce sex -specific epigenetic modifications of hypothalamus InsR, thereby predisposing offspring to long-term metabolic dysregulation and obesity." (PMID 41040868, 2025). "Impaired insulin receptor signaling is strongly linked to obesity-related metabolic conditions like non-alcoholic fatty liver disease (NAFLD) and Type 2 diabetes (T2DM)." (PMID 39747658, 2025). "Since PTPRO is involved in the regulation of glucose and lipid metabolism and the inactivation of the insulin receptor, this further suggests a positive correlation between sweetness preference and obesity risk." (PMID 39517154, 2024). "GPX3 has been associated with insulin receptor downregulation in white adipose tissue in obese insulin-resistant mouse models and in humans with obesity." (PMID 35511873, 2022). "Disruption of insulin receptors in the brain results in obesity-associated IR, whereas restoration of brain insulin receptor function prevents diabetes in the preclinical animal model." (PMID 36134657, 2022). "(2012) which shows that fat specific IGF1R and insulin receptor double knock out mice were resistant to age-associated and diet-induced obesity and glucose intolerance." (PMID 36353242, 2022). "The children who were breastfed showed higher expressions of SLC27A2, FASN, PPARα, and INSR, and were at lower risk to develop obesity." (PMID 34073649, 2021). "Among other lines of evidence, the connection between obesity, hyperinsulinemia and enhanced cancer risk provides a biologically plausible rationale for a key role of insulin and the INSR in breast cancer initiation and/or progression." (PMID 32637033, 2020). "For instance, obesity-induced miR-15b and miR-195 overexpression is linked to the pathogenesis of IR in liver by INSR targeting." (PMID 33212990, 2020). "This is also consistent with fat-specific loss of the insulin receptor resulting in decreased fat mass, and protection from obesity." (PMID 33006363, 2020). "• In mice, genetic lowering of insulin levels or selective genetic disruption of the insulin receptor in adipocytes causes prevention or remission of obesity." (PMID 30541568, 2018). "Sub-cellular network analysis demonstrated the shared biological significance underlying three canonical signaling pathways: insulin receptor, leptin signaling in obesity, and T2D." (PMID 27623749, 2016). "FIRKO mice, with fat-specific disruption of the insulin receptor gene, have a low fat mass, loss of normal relationship between leptin and bodyweight, protection against hypothalamic lesion-induce obesity and an increase in mean lifespan." (PMID 26945906, 2016). "To determine the role of insulin receptors in the reproductive neuroendocrine dysfunction associated with obesity, we used a mouse model of insulin receptor (IR) deletion in kisspeptin neurons and induced hyperinsulinemia with high fat feeding." (PMID 25946091, 2015). "In Zucker fatty rats, obesity was associated with lower hippocampal insulin receptor protein levels." (PMID 25257559, 2014). "TNF-α is produced by adipocytes also in response to obesity, causing increased expression of the transcription factor NFκB, and leading eventually to down-regulation of the insulin receptor and the major insulin-responsive glucose transporter GLUT4." (PMID 17107852, 2006). "Obesity has been linked with increased endoplasmic reticulum stress, which leads to suppression of insulin receptor signaling via hyperactivation of Jnk and subsequent serine phosphorylation of IRS-1." (PMID 16961925, 2006). "Although speculative, INSR plays a role in insulin signalling, and its linkage to ccRCC raises the possibility that it may in part mediate the obesity associated risk of RCC." (PMID 41326661, 2025). "Obesity and related abnormalities may impair the brain glucocorticoids, leptin, and insulin receptor signaling that are linked to depressive symptoms." (PMID 38418418, 2024).
Obesity (continued). "Furthermore, prior research has suggested that genetic variations in insulin receptor genes can elevate the risk of obesity-related cancers." (PMID 38572476, 2024). "The authors also confirmed that in acinar cells with a KRAS mutation, INSR is essential under conditions of high-fat diet-induced obesity for the hyperinsulinemia-driven formation of PanINs; INSR knockout can inhibit PDAC development associated with hyperinsulinemia." (PMID 38982491, 2024). "Thus, insulin receptor signalling has also been associated with GnRH dysregulation leading to LH secretion and reproductive dysfunction in obesity." (PMID 37223019, 2023). "When applied concurrently to mouse striatal slices, the effect of insulin plus leptin on evoked [DA]o is not additive, suggesting the elevated leptin levels that accompany obesity might also contribute to the loss of brain InsR sensitivity in this state." (PMID 36979453, 2023). "Since we observed normal glucose tolerance under an NCD, we then tested whether placental InsR reduction increased the risk of obesity and metabolic dysfunction in the offspring under a diet-induced obesogenic challenge." (PMID 35327377, 2022). "Moreover, obesity or hyperglycaemia can cause up-regulation of hepatic expression of the immature form of Bace1 that is implicated in insulin receptor shedding." (PMID 35873003, 2022). "Finally, diet-induced obesity resulted in a loss of insulin-induced increases in NAc excitatory transmission and a reduction in NAc insulin receptor surface expression." (PMID 33514676, 2021). "Furthermore, obesity resulted in a loss of insulin receptor-mediated increases in excitatory transmission and a reduction in NAc insulin receptor surface expression, while preserving reductions in transmission mediated by IGF receptors." (PMID 33514676, 2021). "This suggests a mechanism by which impaired neuronal insulin receptor signaling, a hallmark of diet-induced obesity, may contribute to impaired DA transmission." (PMID 29698491, 2018). "Taken together, our data indicate that disruption of the insulin receptor in myeloid cells specifically interferes with the obesity-associated recruitment of macrophages to adipose tissue and ultimately leads to reduced local expression of cytokines and chemokines in WAT." (PMID 20463885, 2010). "According to these data, higher expressions of SLC27A2, FASN, PPARα, and INSR genes in the children’s blood reflected a protective role of breastfeeding, as these genes are indicators of a lower risk of developing insulin resistance and dyslipidemia linked with obesity in children." (PMID 34073649, 2021). "Further, obesity was associated with hyperinsulinemia and caused abnormalities in the insulin signaling pathway, which may impact the expression and localization of insulin-related factors, such as InsR, in breast cancer." (PMID 29234306, 2017). "Moreover, there are some data showing that obesity could also cause ER stress, which, in turn, results in inhibition of insulin receptor signaling through hyperactivation of JNK and subsequent serine phosphorylation of insulin receptor substrate-1." (PMID 27983710, 2016). "TNF-α inhibits the tyrosine kinase phosphorylation of the insulin receptor, which results in IR and obesity in PCOS." (PMID 40179096, 2025). "HFD causes obesity, increases inflammatory cytokines (e.g., TNF-α, IL-6), and promotes lipid accumulation in the liver, which impairs insulin receptor function." (PMID 40689212, 2025). "In obesity, its hypothalamic upregulation impairs insulin receptor- and STAT3-mediated leptin pathways, particularly in proopiomelanocortin neurons." (PMID 40699839, 2025). "Impaired insulin receptor function and its downregulation are the fundamental cause of several metabolic disorders, including T2DM, NAFLD, Obesity, etc." (PMID 39747658, 2025).
Obesity (continued). "TNF-α is one of the key mediators of obesity-associated inflammation and can inhibit insulin signaling by activating the JNK/NF-κB pathways, impairing insulin receptor phosphorylation, and contributing to hepatic lipotoxicity." (PMID 40862455, 2025). "Altered INSR levels and kinase activity have been documented in individuals with obesity and NAFLD, potentially linked to the downregulation of INSR induced by high-fat diet (HFD) conditions." (PMID 39747658, 2025). "In rats with diet-induced obesity, mulberry leaf extracts increased insulin receptor expression in muscle and adipose tissue." (PMID 40431370, 2025). "It is also evident that reduction of obesity reduces the quantity of white adipose tissue, which reduces body weight that also involved in the improvement of sensitivity of insulin receptor (IR) too." (PMID 40126146, 2025). "Sex-differential disease-related genes include those associated with obesity (PPARG, INSR), cancer (FGFR1, CD22), and immunity (IL6R, IL3RA)." (PMID 40707586, 2025). "The roles of PTPRO have been reported to involve the control of glucose and lipid metabolism, obesity-induced systemic inflammation, and the inactivation of the insulin receptor." (PMID 39275286, 2024). "We used various combinations of keywords such as “hypoxia”, “obesity”, “insulin receptor”, “adipose tissue”, “adipokine”, “dysfunction”, “inflammation”, and “microRNA” to guide our search." (PMID 39337290, 2024). "In the setting of diet-induced hyperinsulinaemia and obesity, insulin dose-dependently increases the formation of acinar to ductal metaplasia via trypsin and the insulin receptor (InsR)." (PMID 39090116, 2024). "The absence of JNK1 led to decreased adiposity, significantly improved insulin sensitivity, and enhanced insulin receptor signaling capacity in dietary and genetic (ob/ob) models of mouse obesity." (PMID 36984693, 2023). "Because both obesity and gestational diabetes are a pre-disposition to PE, researchers have studied the role of hyperglycemia and InsR/mTOR in the context of PE." (PMID 36992811, 2023). "Consistent with the role of InsR in promoting inflammation and immunity, InsR signaling has been shown to dampen regulatory T cell (Treg) function in the setting of obesity and aging." (PMID 36992811, 2023). "In contrast, it will be interesting to examine to what extent T cells, which only upregulate InsR upon activation, can become insulin resistant, and the metabolic and immune signals that promote IR in T cells during infection and obesity." (PMID 36992811, 2023). "In mice with diet-induced obesity, deletion of enzymes required for reduction of methionine sulfoxide resulted in diminished insulin receptor function, highlighting a potential role of protein oxidation in insulin signaling." (PMID 35323708, 2022). "We observed no changes in POMC neurons in females, while there was a significant loss of POMC neurons in microglia-InsR-KO male mice, compared to microglia-InsR-Ctrl in obesity." (PMID 35328354, 2022). "Our results demonstrate a sex-dependent effect of microglial InsR-signaling in physiology and obesity, and stress the importance of a heterogeneous approach in the study of diseases such as obesity and T2DM." (PMID 35328354, 2022). "Several studies identified PTPN1, a major negative regulator for insulin receptor signaling, as an ideal therapeutic target for intervention in type 2 diabetes and obesity." (PMID 35449053, 2022). "Critical role of brain insulin receptors (InsR) is indicated by the hyperphagia, obesity, and increased fat mass resulting from knockout of CNS InsR." (PMID 36244663, 2022). "In this study, we showed that microglial insulin signaling plays a sex-dependent role in the control of systemic energy homeostasis, with microglial InsR being involved in the progression of obesity most prominently in female mice." (PMID 35328354, 2022).